OTX2 (orthodenticle homeobox 2)
Diseases named in the same sentence as OTX2 in open-access papers (continued):
Sharing a sentence is not in itself a finding about the gene and the disease.
retinopathy (1 paper, 2024). "We explored DNA methylation levels at chr14:77736811 (NGB) and chr14:57265055 (OTX2) in 9 T2D retinopathy cases and 66 T2D retinopathy controls, selected from the TwinsUK discovery and replication T2D cases." (PMID 38574408, 2024).
OTX2 also shares sentences with these, for which no sentence is quoted: holoprosencephaly (2 papers); achromatopsia (1); adenocarcinoma (1); age-related macular degeneration (1); amyotrophic lateral sclerosis (1); and deafness, autosomal dominant 23 (1); anemia (1); autosomal dominant vitreoretinochoroidopathy (1); Bardet-Biedl syndrome (1); brain malformations (1); cardiovascular disease (1); Cerebellar medulloblastoma (1); cerebellar tumours (1); cerebral infarction (1); craniopharyngioma (1); deafness (1); developmental eye defect (1); ear abnormalities (1); early onset retinal dystrophy (1); embryonal carcinoma (1); endocrinopathy (1); Familial adenomatous polyposis (1); female infertility (1); gastrointestinal tumours (1); genetic disorder (1); glaucoma (1); glioblastoma multiforme (1); haematopoietic cancers (1); hemifacial microsomia (1); Infertility (1).
A further 16 diseases each share a sentence with OTX2 in 1 paper.